AFP (alpha fetoprotein)
Diseases named in the same sentence as AFP in open-access papers (continued):
Sharing a sentence is not in itself a finding about the gene and the disease.
liver cancer (continued). "Importantly, we compared the performance of our HCC screening model with AFP in distinguishing HCC patients who were AFP-normal and early-stage HCC patients (Barcelona Clinic Liver Cancer [BCLC] stage 0-A) from the high-risk population." (PMID 35027051, 2022). "However, these screening methods still have major shortcomings, such as a low AFP-positive rate for early liver cancer." (PMID 35943150, 2022). "The overexpression of cell cycle control genes may be a critical molecular mechanism for re-activating AFP expression in liver cancer." (PMID 35252202, 2022). "Additional TCRL-based CAR-T examples targeting hematological malignancies and solid tumors can be found against the intracellular onco-protein WT1, specific liver cancer marker alpha-fetoprotein (AFP), and gp100, all showing promising results in pre-clinical studies." (PMID 36611821, 2022). "Furthermore, alpha-fetoprotein measurement, a tumour marker supporting diagnosis of liver cancer, was performed in only 115 (18.2%) patients." (PMID 36678401, 2022). "CircSMARCA5 can not only screen for liver cancer but also has the ability to distinguish between liver fibrosis and hepatitis, and may be used as a screening indicator for cancer together with alpha-fetoprotein." (PMID 35712125, 2022). "Therefore, the determination of AFP-L3 levels is crucial for differentiating between benign and malignant liver diseases, and the early diagnosis of liver cancer when there is AFP positivity." (PMID 35307694, 2022). "Gemcitabine showed a 29.7% inhibition rate in the current in vitro HDS and was significantly correlated with AFP expression; however, the specific mechanism responsible for gemcitabine's unique effect on AFP-positive liver cancer cells remains unknown." (PMID 35127582, 2022). "Before propensity score matching, differences could be observed between the sorafenib and lenvatinib groups regarding the Barcelona Clinic liver cancer stage, prothrombin, alpha fetoprotein, and blood urea nitrogen levels." (PMID 35583540, 2022). "At present, the application of AFP in early screening of liver cancer has been controversial." (PMID 36119529, 2022). "Therefore, AFP is an imperfect surveillance tool making it imperative for the hepatology and oncology community to find a reasonably suitable hepatic cancer biomarker." (PMID 35268381, 2022). "Widely used in the diagnosis of liver cancer, AFP is considered an important serological marker." (PMID 35919232, 2022). "Among them, typical liver cancer stem cell markers such as AFP and keratin 19 (KRT19) were upregulated in FOXM1-high HCC, whereas typical mature hepatocyte markers such as solute carrier organic anion transporter family member 1B1 (SLCO1B1) and cytochrome P450 3A4 (CYP3A4) were downregulated." (PMID 35955438, 2022). "Previous studies have shown that the ability of AFP to diagnose liver cancer is relatively poor." (PMID 36119529, 2022). "According to investigations, 32 to 59% of liver cancer patients have normal AFP levels." (PMID 34238253, 2021). "We also detected a clear upregulation of several liver cancer marker genes such as AFP, GPC3, SAA1, and VIL1 in transformed iHeps and in CMT + sgTP53 tumors compared to control fibroblasts; AFP was also found among the most enriched genes in both CMT + sgTP53- and CMT-transformed iHeps." (PMID 34302118, 2021). "In addition, the sunflower-like structure has achieved the detection of ultra-low-concentration liver cancer cell marker AFP, which has further improved the practical application development of SERS spectroscopy detection technology." (PMID 33672380, 2021). "Alpha fetoproteins (AFP) are the proteins being present in the serum of the liver, and their level rises in the patients with liver cancer; they are measured as a tumor marker and as a result of the effective treatment of the tumor, its level is being reduced in the serum." (PMID 34327239, 2021).
liver cancer (continued). "The sensitivity of AFP to HCC in phase A of Barcelona clinical liver cancer is less than 50%." (PMID 34348726, 2021). "Given that serum AFP level is a prognostic factor of liver cancer, and neutrophil-to-lymphocyte ratio (NLR) and albumin bilirubin (ALBI) grade are also common indicators for monitoring the prognosis of liver cancer, we used the same method to calculate the AUCs of AFP, NLR and ALBI, respectively." (PMID 33536005, 2021). "AFP has been reported to play an important role in the development of liver cancer." (PMID 33765973, 2021). "The serum level changes of characteristic tumor markers (such as CEA in colon cancer, AFP in liver cancer, and PSA in prostate cancer) of various types of tumors after the treatment with PD-1 inhibitors were compared with the evaluation results of RECIST standard and HPD standard in this study." (PMID 34239621, 2021). "DCP>40 mAU/mL or AFP-L3/AFP>15% suggests the possibility of liver cancer." (PMID 34277397, 2021). "AFP, used as a liver cancer biomarker for over 30 years, may also be elevated to varying degrees in patients with gastric cancer, pancreatic cancer, or lung cancer." (PMID 34335759, 2021). "There were no relevant differences between the two groups in the baseline characteristics, age, sex, ECOG performance, cause of liver disease, Barcelona Clinic Liver Cancer (BCLC) stage, macroscopic vascular invasion, extrahepatic spread, Child‐Pugh status or serum AFP level." (PMID 33481328, 2021). "Considering the importance of AFP in the development of liver cancer, we considered whether icaritin inhibits the proliferation of liver cancer cells by down-regulating AFP protein expression." (PMID 33765973, 2021). "Additionally, AFP (α-fetoprotein), which was reported as a biomarker in liver cancer cell growth and apoptosis, was downregulated after EPS364 treatment." (PMID 33809909, 2021). "AFP was discovered more than 50 years ago and is not a very accurate diagnostic biomarker for liver cancer." (PMID 34238253, 2021). "Recently, a number of disease-biomarker aptamers were successfully selected by microfluidic technology, such as platelet derived growth factor BB (PDGF-BB) protein for various pathological states, myoglobin for cardiovascular disease, and alpha-fetoprotein for liver cancers." (PMID 34604229, 2021). "Therefore, serum AFP is considered as the standard biomarker for clinical diagnosis of liver cancer." (PMID 34306031, 2021). "AFP possesses a variety of biological functions, including its diagnosis in liver cancer." (PMID 35046917, 2021). "When requiring >95% specificity in the HDs of the training set (specificity: 96.2%), the model accurately predicted the identity of all AFP-positive patients (sensitivity: 100%) and discriminated liver cancer patients from most CHB patients (specificity: 91.7%)." (PMID 33391469, 2021). "A single detection of AFP or AFP-L3 had a very high differential diagnosis value for liver cancer and non-liver cancer, and the combined detection of these two could help reduce the clinical misdiagnosis rate." (PMID 34475930, 2021). "The results of the present study also confirmed that Hsp90α could assist AFP in liver cancer diagnosis by improving the sensitivity and specificity of HCC." (PMID 34348726, 2021). "AFP is an important indicator for screening liver cancer and prognosis." (PMID 32117619, 2020). "AFP is a glycoprotein biomarker derived from AFP is widely used in liver cancer diagnosis." (PMID 33585001, 2020). "The sensitivity of the classic liver cancer diagnosis marker AFP is less than 80%." (PMID 33372599, 2020). "Also, the human AFP (a specific liver cancer marker) secretion in the mouse serum after paOAd infection was significantly decreased by blue light irradiation." (PMID 32703933, 2020). "M4 and M5 module were significantly related to AFP high expressing liver cancer." (PMID 31897235, 2020).
liver cancer (continued). "Comparison between AFP and SEPC in the diagnosis of liver cancer, with pathological diagnosis as the gold standard, needs to be conducted in the future to explore whether SEPCs perform better than AFP in HCC." (PMID 33312206, 2020). "AFP is well known clinical marker in the diagnosis and treatment of liver cancer." (PMID 31973032, 2020). "AFP is a widely used serum biomarker for detecting liver cancer worldwide." (PMID 32426269, 2020). "Alpha‐fetoprotein (AFP) is a well‐known biomarker in liver cancer progression and recurrence." (PMID 32779318, 2020). "Five gene modules were revealed for liver cancer and AFP belonged to M4 module." (PMID 31897235, 2020). "In addition, high expression of AFP defined a subtype of liver cancer with distinct gene expression profiles and clinical features." (PMID 31897235, 2020). "In addition to AFP, plasma cell‐free DNA sequencing is a useful tool for primary liver cancer diagnoses." (PMID 32458568, 2020). "AFP was highly expressed in a subset of liver cancer compared to normal liver." (PMID 31897235, 2020). "Similarly, Cu-MOF-NPs can detect alpha-fetoprotein (AFP) for liver cancer diagnosis as well as triiodothyronine hormone (T3) for thyroid disease diagnosis." (PMID 34138131, 2020). "Similarly, in an independent dataset GSE14520, liver cancer patients with high serum AFP levels also had significantly worse overall survival than patients with low serum AFP levels (Log-rank test: p = 0.024)." (PMID 31897235, 2020). "We found that AFP was significantly enriched in iClust1 subtype of liver cancer." (PMID 31897235, 2020). "Previous reviews have found that hsa_circ_0004018 (circSMYD4) has a significantly lower level in liver cancer tissues than in adjacent tissues and possesses supersensitivity to alpha-fetoprotein (AFP), and thus it can be used as a potential biomarker for the diagnosis of HCC." (PMID 33292243, 2020). "AFP, DPC and AFP-l3 biomarkers are usedin combination every six months for liver cancer detection." (PMID 33585001, 2020). "Although aberrant AFP expression is mainly found in liver cancer, it could also be found occasionally in gastric cancer, breast cancer 2, lung cancer, pancreatic cancer." (PMID 31897235, 2020). "For liver cancer, the alpha fetoprotein (AFP) is the most used." (PMID 30669634, 2019). "AFP is a widely used, yet imperfect biomarker for detection of liver cancer." (PMID 30675135, 2019). "However, when suffering from liver cancer, the AFP concentration in serum will increase significantly." (PMID 31336606, 2019). "For example, prostate-specific antigen (PSA) has been used as an effective indicator of prostate cancer so as to improve diagnostic accuracy of prostate cancer, and the express level of alpha-fetoprotein (AFP) is an important biomarker for the diagnosis of primary liver cancer." (PMID 34138055, 2019). "This indicated that the GP73 was superior than AFP in detecting liver cancer." (PMID 30341783, 2019). "Hence, to determine AFP concentration in human serum is extremely important for patients who suffer from liver cancer." (PMID 31336606, 2019). "Alpha-fetoprotein (AFP) with a molecular weight of approximately 70 kDa is always considered as a vital and specific biomarker for diagnosing, treating, and the prognosis of liver cancer." (PMID 31336606, 2019). "Thus, the AFP level can provide a good standard for the early diagnosis of liver cancer, and will benefit for early treatment and help to prolong survival and improve the quality of life." (PMID 31336606, 2019). "AFP is commonly used to assist in the diagnosis of liver cancer." (PMID 31501420, 2019). "Besides, regular follow-up is necessary for cancer patients who suffer from operation or chemoradiotherapy, and the examination of tumor markers is indispensable—similar to the function of the index AFP (alpha fetoprotein) in liver cancer." (PMID 30925885, 2019).
liver cancer (continued). "Label-free detection of lung cancer and liver cancer also witnessed a further step with multianalyte of cytokeratin fragment 21-1 (CYFRA 21-1, biomarker for lung cancer) and α-fetoprotein (AFP, biomarker for liver cancer) was simultaneously detected in human serum." (PMID 31569330, 2019). "However, the combined diagnosis of GP73 and AFP is more likely to increase the detection rate of liver cancer." (PMID 30341783, 2019). "Besides liver cancer, malignant tumors from stomach, pancreas, and reproductive system are often accompanied by a small amount of increased AFP." (PMID 29805966, 2018). "However, the positive predictive value of alpha-fetoprotein (AFP) in the diagnosis of primary liver cancer is only 67.8–74.4%." (PMID 30587152, 2018). "Most liver cancer cells express a high level of AFP and HSPs in the cytoplasm and HSPs could transport cytoplasm AFP to the cell membrane and release AFP antigen to serum, which indicates that AFP could be an ideal target for immune attack." (PMID 29805966, 2018). "First, AFP has poor sensitivity as a liver cancer screening biomarker, especially for early-stage disease, and thus may not be useful for mass screening." (PMID 30143694, 2018). "AFP-modified immune cell vaccine or peptide vaccine has displayed the specific antitumor immunity against AFP-positive tumor cells and laid a better foundation for the immunotherapy of liver cancer." (PMID 29805966, 2018). "α fetal protein (AFP), which is a serological marker of liver cancer, was used as a model analyte." (PMID 28448741, 2018). "MLAgNPs fundamentally lessened the AFP level compared with the DEN-initiated liver cancer group." (PMID 35540326, 2018). "When transformed, the liver cancer cells can regain the ability to synthesize AFP." (PMID 29805966, 2018). "Since AFP promotes the proliferation of liver cancer, it could be a new target for the immune therapy of liver cancer." (PMID 29805966, 2018). "Except for its diagnosis in liver cancer, AFP has become a target for liver cancer immunotherapy." (PMID 29805966, 2018). "Furthermore, our findings provide a novel mechanism on the autophagic function of EGCG towards AFP and the unique advantages of autophagy in the prevention and treatment of liver cancer, supporting the health benefits of green tea." (PMID 29095434, 2017). "Here we showed that AFP is detected in the hepatocytes of liver cancer rats." (PMID 29268718, 2017). "Moreover, AFP staining in liver cancer is only reported to be cytoplasmic while both intranuclear and cytoplasmic staining was observed with TCDD in males at 30 μg/kg, the significance of which is unclear." (PMID 28922406, 2017). "The radiological and laboratory investigations done revealed the metastatic compression originating from a liver cancer with elevated alpha-fetoprotein and aspartate transaminase, positive hepatitis B surface antigen, and multiple metastasis in the lungs, mediastinum, ribs, iliac, and peritoneum." (PMID 29230336, 2017). "Notably, recent reports and our previous study showed that primary liver cancer, which usually produces AFP, also expresses high level of XIAP." (PMID 27057629, 2016). "In addition, role of HBV x protein (HBx) on the up-regulation of alpha-fetoprotein receptor (AFPR) and AFP expression has been noticed in HBV-mediated liver cancer." (PMID 26784252, 2016). "Interestingly, GPC3 level is more frequently elevated than AFP level (88% versus 55%) in patients with liver cancer, and especially in those with HCC tumors < 3 cm (77% versus 43%)." (PMID 27655712, 2016). "Existing prognostic factors such as serum alpha-fetoprotein (AFP), multinodular tumors, tumor Barcelona-clinic liver cancer (BCLC) stage, and tumor size have been identified in previous studies, their prognostic value warrants more investigation and broader applications." (PMID 28002346, 2016).
liver cancer (continued). "After control for case-control status and established liver cancer risk factors, coffee intake was positively associated with C-peptide and inversely with IL-6, GLDH, ALT, AST, GGT, alkaline phosphatase, total bilirubin, and AFP." (PMID 26561631, 2015). "AFP in our dataset was elevated in 94 % of liver cancer patients, but 10 cases were AFP-negative." (PMID 26561538, 2015). "A previous study demonstrated that AFP expression is frequently upregulated in liver cancer cells." (PMID 25667643, 2015). "AFP is reported to be highly fucosylated and specific in hepatic cancer serum." (PMID 23894390, 2013). "Factors associated with complete liver cancer screening (by both ultrasonography and serum alpha-fetoprotein testing) and incomplete screening compared to never-screening by polychotomous logistic regression." (PMID 23840846, 2013). "All this indicates that AFP promoter as a potential regulatory element in liver cancer therapy." (PMID 22040050, 2011). "As such, we believe that Ad.SPDD-HCCS1 could bee a promising candidate for the treatment of AFP positive liver cancer." (PMID 22040050, 2011). "This indicates that AFP promoter may be a specific anti-liver-cancer cell promoter, and combines it with other safety regulatory element will possibly improve its safety further." (PMID 22040050, 2011). "The high levels of AFP are an indication of the specific activity of the AFP promoter in liver cancer, and it may be used to improve the safety of gene therapy in AFP positive liver cancer cells." (PMID 22040050, 2011). "Moreover, our patient had a normal liver function test and a normal alpha-fetoprotein and was asymptomatic from his primary liver cancer." (PMID 18570669, 2008). "our results provide evidence that AFP could promote the escape of liver cancer cells from immune surveillance through blocking the caspase signal pathway of tumor cells and triggering the Fas/FasL interaction between tumor cells and lymphocytes." (PMID 16080799, 2005). "We presume that the altered serum AFP level is the cause of such changes rather than a coincident phenomenon and should be responsible for the malignant progression of liver cancer." (PMID 16080799, 2005). "As for AFP, studies have shown that it can significantly influence the immune microenvironment in liver cancer through multiple mechanisms, including its effects on liver cancer stem cells, various immune cells, fibroblasts, and the endothelial-to-mesenchymal transition process." (PMID 39958339, 2025). "Therefore, AFP is no longer solely a diagnostic marker for liver cancer but also a crucial element in understanding cancer biology and developing treatment strategies for other cancers expressing this protein." (PMID 40430002, 2025). "Given the well-known role of AFP in reflecting the tumor burden and biological behavior in liver cancer, we hypothesized that an early AFP response could indicate favorable tumor dynamics in response to therapy, whereas a lack of response may suggest the need for treatment adjustments." (PMID 39767676, 2024). "Additionally, lower Barcelona Clinic Liver Cancer and Child Turcotte Pugh classification were associated with negative AFP and PIVKA-II (P < .05 for each)." (PMID 39432605, 2024). "Therefore, AFP is a key cytokine that inhibits liver cancer cell phagocytosis by macrophages." (PMID 38660138, 2024). "However, there are also some patients with liver cancer who have normal AFP levels or only mildly elevated AFP levels, which may be related to differences in the type, location, and size of the tumor and the regulatory mechanism of AFP secretion." (PMID 38660138, 2024). "AFP levels correlated with the high numbers of pDCs, tumor metastasis, and increased tumor infiltration of Tregs.Studies have confirmed that AFP isolated from human umbilical cord blood acts on monocytes in patients with liver cancer, inhibiting the conversion of monocytes into mature DCs." (PMID 38660138, 2024).